ADAMTS1 (ADAM metallopeptidase with thrombospondin type 1 motif 1)
Diseases named in the same sentence as ADAMTS1 in open-access papers (continued):
Sharing a sentence is not in itself a finding about the gene and the disease.
aneurysm (3 papers, 2017 to 2021). Bulging or ballooning in an area of an artery secondary to arterial wall weakening. "The importance of ADAMTS proteins in the development and progression of aneurysms is also confirmed by reports indicating that ADAMTS1 deficiency reduces the formation and rupture of aneurysms." (PMID 34884962, 2021). "Mice overexpressing ADAMTS-1 in an angiotensin II induced AAA develop aneurysm to the same extent as wild type mice and therefore ADAMTS-1 probably plays minor role in AAA progression." (PMID 28570682, 2017). "Research indicates that an increased expression of the majority of the investigated ADAMTS, especially ADAMTS-1 and ADAMTS-4 members on mRNA level, has a large share in the development of aneurysms associated with the infiltration of inflammatory cells and the destruction of the aortic walls." (PMID 34884962, 2021).
Cachexia (3 papers, 2018 to 2022). Severe weight loss, wasting of muscle, loss of appetite, and general debility related to a chronic disease. "ADAMTS-1 was originally identified in a cachexia model and cachexia has overlapping symptoms with HEG (appetite loss, weight loss, and muscle wasting)." (PMID 35725415, 2022).
colorectal tumor (3 papers, 2007 to 2015). "Using RT-PCR, the expression of ADAMTS-1, -4, -5 and ADAMTS-20 was estimated in colorectal tumors of different cancer stage and anatomic site and 3 cell lines of different aggressiveness." (PMID 25786261, 2015).
fibrosarcoma (3 papers, 2016 to 2025). A malignant mesenchymal fibroblastic neoplasm affecting the soft tissue and bone. "ADAMTS1 decreases fibrosarcoma cell proliferation and migration velocity by disrupting HGF/c-MET signaling." (PMID 35625488, 2022). "In HT1080, a cell line derived from fibrosarcoma, ADAMTS-1 is present mainly in the cytoplasm." (PMID 27764205, 2016).
gastric cancer (3 papers, 2015 to 2021). A primary or metastatic malignant neoplasm involving the stomach. "A significant association was observed between the ADAMTS1 methylation status and the depth of tumor invasion and tumor, node, metastasis stage in primary gastric cancer." (PMID 25936341, 2015). "The present study aimed to examine the expression of ADAMTS1 in gastric cancer and its association with aberrant methylation." (PMID 25936341, 2015). "In addition, the association between ADAMTS1 methylation and clinicopathological features in were investigated in patients with primary gastric cancer." (PMID 25936341, 2015). "An understanding of the precise mechanism of the down-=regulation of ADAMTS1 in gastric cancer needs requires further investigation." (PMID 25936341, 2015). "Our previous study demonstrated that decreased expression of ADAMTS1 is observed in primary gastric cancer." (PMID 25936341, 2015). "In conclusion, the results of the present study demonstrated that the mRNA expression of ADAMTS1 was significantly lower in gastric cancer cell lines." (PMID 25936341, 2015). "The relative mRNA expression levels of ADAMTS1 were significantly lower in the methylated gastric cancer cell lines, compared with the unmethylated gastric cancer cell lines." (PMID 25936341, 2015). "The mRNA expression of ADAMTS1 was significantly lower in 60% (3 of 5) of the gastric cancer cell lines." (PMID 25936341, 2015). "In the present study, the mRNA expression of ADAMTS1 was significantly lower in the gastric cancer cell lines compared with the normal gastric cell line." (PMID 25936341, 2015). "Therefore, further biological experiments in vivo and in vitro are required to confirm the functions of OGN, JAM2, RERG, OLFML2B and ADAMTS1 genes in gastric cancer in the future." (PMID 33015704, 2020). "ADAMTS1 expression was dysregulated in primary gastric cancer and paired lymph node metastasis." (PMID 33015704, 2020). "In addition, the downregulation in the expression of ADAMTS1 was correlated with methylation of its promoter in the gastric cancer cell lines and gastric cancer tissues." (PMID 25936341, 2015). "Together, these findings support the hypothesis that ADAMTS1 functions as a tumor inhibitor in the gastric cancer." (PMID 25936341, 2015). "Therefore, the aberrant methylation of ADAMTS1 may be involved in the development and progression of gastric cancer." (PMID 25936341, 2015). "Statistically, the mRNA expression of ADAMTS1 was significantly lower in the BGC-823, MGC-803, HGC-27 and AGS gastric cancer cell lines, compared with the GES-1 normal gastric cell line." (PMID 25936341, 2015). "The expression of ADAMTS1 was undetectable in the MGC-803, HGC-27 and AGS gastric cancer cell lines of the six cell lines examined." (PMID 25936341, 2015). "Furthermore, the expression of ADAMTS1 was significantly restored following treatment with the 5-Aza-2′-deoxycytidine demethylating agent in the MGC-803, HGC-27 and AGS gastric cancer cell lines, and the demethylation of the MGC-803 cell line inhibited cell invasion." (PMID 25936341, 2015).
ischemia (3 papers, 2020 to 2025). A hypoperfusion of the BLOOD through an organ or tissue caused by a PATHOLOGIC CONSTRICTION or obstruction of its BLOOD VESSELS, or an absence of BLOOD CIRCULATION. "Next, PKCβ inhibition abolished VEGF upregulation of A-disintegrin and metalloproteinase with thrombospondin motifs 1 (ADAMTS1) to promote endothelial proliferation and angiogenesis in a mouse model of ischemia-induced retinal neovascularization." (PMID 40926896, 2025).
metastatic carcinoma (3 papers, 2014 to 2025). A carcinoma which has spread from the original site of growth to another anatomic site. "Our data demonstrated a new insight into the roles of C‐mannosylation in ADAMTS1 and that C‐mannosylation might be a potential target for ADAMTS1‐related metastatic cancer." (PMID 40878842, 2025). "ADAMTS1 is a protease commonly up-regulated in metastatic carcinoma." (PMID 25481245, 2014).
prostate tumors (3 papers, 2010 to 2021). "That increased expression of ADAMTS1 is associated with a less malignant phenotype of androgen-independent prostate tumors has also been shown in PC-3 tumors." (PMID 20546609, 2010). "Loss of ADAMTS1 was associated with small diameter vessels that have been associated with more aggressive prostate tumors." (PMID 20546609, 2010). "In prostate tumors, expression of ADAMTS1 was directly correlated to the diameter of blood vessels, thus proving a pro-angiogenic role of ADAMTS1." (PMID 35053160, 2021). "Future studies will focus on elucidating the relationship between EAF2, ADAMTS1 and the stromal microenvironment in prostate tumor development and progression." (PMID 24260246, 2013). "The results from this study demonstrate that ADAMTS1 is an important regulatory factor of angiogenesis and tumor growth in prostate tumors." (PMID 20546609, 2010). "The present study demonstrates that ADAMTS1 is an important regulatory factor of angiogenesis and tumor growth in prostate tumors, where modified ADAMTS1 expression resulted in markedly changed blood vessel morphology, possibly related to altered TSP1 levels." (PMID 20546609, 2010). "The aim of this study was to investigate the function of ADAMTS1 in prostate tumors." (PMID 20546609, 2010).
pulmonary fibrosis (3 papers, 2021 to 2023). Chronic progressive interstitial lung disorder characterized by the replacement of the lung tissue by connective tissue, leading to progressive dyspnea, respiratory failure, or right heart failure. "On the other hand, in a pulmonary fibrosis rat model induced by intra-tracheal injection of bleomycin, it was observed that prodigiosin attenuates pulmonary fibrosis by inhibiting miR-410 and leading to the downregulation of the TGFβ1/ADAMTS-1 signaling pathway." (PMID 35743055, 2022). "Moreover, the upregulation of the IFN signaling leads to increased bradykinin signaling (via ACE2 upregulation), that together with higher levels of CPA3 and ADAMTS1 can lead to lung fibrosis." (PMID 33479353, 2021).
renal fibrosis (3 papers, 2022 to 2025). A final common manifestation of a wide variety of chronic kidney diseases characterized by glomerulosclerosis and tubulointerstitial fibrosis. "It has been reported that hypoxia also has been linked to increased expression of ADAMTS-1 in renal fibrosis tissues." (PMID 36338393, 2022). "Specifically, ADAMTS-1 promoting renal fibrosis through affecting vascular stability, collagen deposition and ECM modulation, which is crucial in DKD progression." (PMID 40825025, 2025). "ADAMTS-1 is critical for kidney development, and lack of ADAMTS-1 may lead to renal fibrosis and dysplasia in mice." (PMID 35883515, 2022).
Stroke (3 papers, 2013 to 2024). Sudden impairment of blood flow to a part of the brain due to occlusion or rupture of an artery to the brain. "Further candidates for the stroke-induced degradation of net components are aggrecanases, e.g., disintegrin and metalloproteinase with thrompospondin motifs (ADAMTS-1, 4, 8 and 15) and neprilysin." (PMID 28860977, 2017). "Surprisingly, whereas mRNA changes were observed in the ipsilateral hemisphere acutely at 6 and 24 hours after stroke onset, the upregulation of the protein levels of ADAMTS-1 and -4 was only observed 5 days after injury." (PMID 24176075, 2013). "Because TNF-α was shown to promote ADAMTS-1 and -4 mRNA levels as well as ADAMTS-4 and -5 protein levels in human astrocyte cultures, it was hypothesized that the increase of TNF-α expression in the acute phase of stroke may be responsible for the upregulation of ADAMTS-1 and -4 by astrocytes." (PMID 24176075, 2013).
aortic aneurysm (2 papers, 2025). A ruptured aneurysm located in the wall of the proximal portion of the descending aorta proceeding from the arch of the aorta. "Up to this point, ADAMTS-1 levels have been shown to correlate with the presence of aortic aneurysms." (PMID 39859253, 2025). "The role of ADAMTS1 in aortic aneurysms and dissections is complex and highly dependent on anatomical location and disease pathogenesis." (PMID 41440846, 2025).
Arthritis (2 papers, 2011 to 2018). Inflammation of a joint. "ADAMTS1 and associated family members may be key enzymes in degradation of cartilage leading to inflammation and arthritis." (PMID 22186957, 2011). "A disintegrin and metalloprotease with thrombospondin type I motifs-1 (ADAMTS1) plays a crucial role in inflammatory joint diseases and its inhibitors are potential candidates for anti-arthritis drugs." (PMID 22186957, 2011).
chondrosarcoma (2 papers, 2019 to 2025). A malignant cartilaginous matrix-producing mesenchymal neoplasm arising from the bone and soft tissue. "Furthermore, it has been reported that in the human chondrosarcoma cell lines C3842 and OUMS‐27, the inflammatory stimulus IL‐1β reduced ADAMTS1 mRNA levels, while hypoxia did not alter ADAMTS1 mRNA in C3842." (PMID 40864881, 2025).
chronic pancreatitis (2 papers, 2019 to 2024). A chronic inflammatory process causing damage and fibrosis of the pancreatic parenchyma. "Furthermore, the investigators found that LRFN5 and PXDN did not exhibit significant methylation frequency in patients with chronic pancreatitis (CP) compared to healthy individuals, providing better distinction than the panel of ADAMTS1 and BNC1 alone." (PMID 38672671, 2024). "Using the combination panel (ADAMTS1 and/or BNC1), 87.5% (7/8) of chronic pancreatitis patients had positive methylation." (PMID 30953539, 2019).
endometrial adenocarcinoma (2 papers, 2010 to 2015). "Next we investigated the site of ADAMTS1 expression in well, moderately and poorly differentiated endometrial adenocarcinomas and proliferative phase endometrium." (PMID 20840749, 2010). "Here we investigated the expression and localisation of ADAMTS1 in endometrial adenocarcinoma and its regulation by PGF2α via the FP receptor." (PMID 20840749, 2010). "ADAMTS1 mRNA and protein expression is elevated in endometrial adenocarcinoma tissues compared with normal proliferative phase endometrium and is localised to the glandular and vascular cells." (PMID 20840749, 2010). "This pattern of expression in endometrial adenocarcinomas is similar to the expression profile for ADAMTS1 in secretory phase human endometrium as reported by Ng and colleagues, where expression is observed in the glandular epithelial and stromal cells." (PMID 20840749, 2010). "Taken together our data highlight a mechanism whereby ADAMTS1, induced by PGF2α-FP signalling, regulates tumour cell invasion and endothelial cell proliferation in endometrial adenocarcinoma." (PMID 20840749, 2010). "In this study, we investigated the expression, regulation and potential role of a disintegrin and metalloprotease with a thrombospondin repeat 1 (ADAMTS1) in endometrial adenocarcinomas." (PMID 20840749, 2010). "We found that the expression of ADAMTS1 was elevated in all endometrial adenocarcinoma samples compared with proliferative phase endometrium (P < 0.05)." (PMID 20840749, 2010). "Since we found ADAMTS1 immunolocalised in the vasculature of endometrial adenocarcinoma, we investigated the regulation of ADAMTS1 in endothelial cells in response to CM from FPS cells." (PMID 20840749, 2010). "We confirmed the vascular localisation of ADAMTS1 in endometrial adenocarcinomas by dual immunofluorescence immunohistochemistry and confocal laser microscopy." (PMID 20840749, 2010). "This study investigates the expression, regulation and role of a disintegrin and metalloproteinase with thrombospondin repeat 1 (ADAMTS1) in endometrial adenocarcinoma cells by PGF2α via the FP receptor." (PMID 20840749, 2010). "We investigated the mRNA expression of ADAMTS1 in human endometrial adenocarcinoma and normal endometrium from the proliferative phase of the menstrual cycle by Taqman Quantitative RT-PCR analysis." (PMID 20840749, 2010). "This study presents novel data demonstrating that PGF2α-FP receptor signalling in endometrial adenocarcinoma cells upregulates ADAMTS1 expression via a Gq-calmodulin-NFAT-dependent pathway." (PMID 20840749, 2010). "In the present study, we found that the expression of ADAMTS1 was upregulated coincident with the FP receptor in well, moderately and poorly differentiated endometrial adenocarcinoma samples compared to normal endometrium from the proliferative phase of the menstrual cycle." (PMID 20840749, 2010). "In contrast to this latter study that reports readily detectable levels of ADAMTS1 throughout the menstrual cycle, in our study we found minimal immunoreactivity for ADAMTS1 in proliferative phase endometrium compared with the different grades of endometrial adenocarcinomas." (PMID 20840749, 2010). "However, the expression and role of ADAMTS1 in endometrial adenocarcinoma has not been studied." (PMID 20840749, 2010). "Under the same experimental conditions, minimal immunoreactivity was observed for ADAMTS1 in proliferative phase endometrium and no immunoreactivity was observed in control sections incubated with IgG from the host species (inset shown for poorly differentiated endometrial adenocarcinoma)." (PMID 20840749, 2010).
endothelial dysfunction (2 papers, 2025). In vascular diseases, endothelial dysfunction is a systemic pathological state of the endothelium (the inner lining of blood vessels) and can be broadly defined as an imbalance between vasodilating and vasoconstricting substances produced by (or acting on) the endothelium. "A notable finding was the discrepancy between in vitro endothelial dysfunction and relatively limited in vivo vascular alterations following ADAMTS1 overexpression." (PMID 41014581, 2025). "This disconnect between in vitro endothelial dysfunction and minimal in vivo vascular remodeling suggests that Adamts1's primary pathological effects in the post‐MI heart may operate through alternative mechanisms beyond direct vascular modulation." (PMID 41014581, 2025). "Second, the current study did not clarify the precise mechanisms by which SPARC and ADAMTS1 contribute to vascular inflammation and endothelial dysfunction." (PMID 40362650, 2025).
female infertility (2 papers, 2017 to 2020). Diminished or absent ability of a female to achieve conception. "We found that furin deletion caused female infertility and follicle arrest before the type 4 and/ 5a stage by causing failure of pro-ADAMTS1 proteolytic processing to ADAMTS1 by FURIN." (PMID 28569793, 2017).
Granuloma (2 papers, 2020 to 2022). A compact, organized collection of mature mononuclear phagocytes, which may be but is not necessarily accompanied by accessory features such as necrosis. "ADAMTS1, gene encodes a disintegrin and metalloproteinase with thrombospondin motif associated with various inflammatory processes and a potentially important regulator of pathogenic granuloma formation in sarcoidosis in both compartments." (PMID 33276795, 2020). "Only six genes (ADAMTS1, HSPB6, NR4A1, CXCL2, NPR1, ITGA9) were exclusively dysregulated in both lung and lymph node in sarcoidosis granulomas but not in CM or TB." (PMID 33276795, 2020).
Hereditary thrombotic thrombocytopenic purpura (2 papers, 2024 to 2026). "Hereditary thrombotic thrombocytopenic purpura (TTP) is a rare autosomal recessive inherited disease caused by an ADAMTS1 gene mutation, resulting in absence or severe deficiency of plasma ADAMTS13 activity." (PMID 41797737, 2026). "A severe deficiency of ADAMTS‐1 activity, with clinical symptoms of acute thrombocytopenia and evidence of microangiopathic hemolytic anemia, constitutes a diagnosis of TTP." (PMID 39070506, 2024).
invasive ductal carcinoma (2 papers, 2016 to 2024). "ADAMTS-1 is present in nuclei of invasive ductal carcinoma cells as dot-like structures." (PMID 27764205, 2016).
ischemic stroke (2 papers, 2013 to 2020). A stroke disorder caused by obstruction of blood flow to the brain, due to thrombotic (local blood clot formation) or embolic (due to a blood clot or other material traveling from another site) event. "Polymorphisms of the ADAMTS1 gene (rs416905 and rs402007) may be associated with ischemic stroke caused by arge artery atherosclerosis." (PMID 32529744, 2020). "To summarize, CNS injuries including ischemic stroke or SCI lead to the upregulation of different combinations of ADAMTS proteoglycanases, respectively ADAMTS-1, -4, -9 and ADAMTS-1, -5, -9." (PMID 24176075, 2013).
oral squamous cell carcinoma (2 papers, 2024 to 2025). "At present, the role of ADAMTS1 in oral squamous cell carcinoma (SCC; OSCC) remains unclear." (PMID 38263290, 2024). "In contrast, ADAMTS1 overexpression promoted lymph node metastasis through the upregulation of EGFR, pEGFR, and pAKT in oral squamous cell carcinoma." (PMID 40867252, 2025).
renal cell carcinoma (2 papers, 2021 to 2024). "In renal cell carcinoma, melatonin-triggered posttranscriptional and posttranslational modification of ADAMTS1 synergistically inhibits renal cell carcinoma." (PMID 34603444, 2021).
uveal melanoma (2 papers, 2016 to 2020). A melanoma derived from melanocytes of the uveal tract. "In this work, we find that the inhibition of the extracellular protease ADAMTS1 alters the endothelial-like properties of uveal melanoma cells in vitro and affects tumor vasculature in vivo." (PMID 32230715, 2020). "With this purpose we obtained xenografts with two uveal melanoma cell lines, MUM2B and MUM2C, which different endogenous levels of ADAMTS1 were previously revealed." (PMID 27120788, 2016).
adenoma (1 paper, 2008). A neoplasm arising from the epithelium. "ADAMTS1, CDKN2A, CRABP1, MLH1, NR3C1, RUNX3, and SCGB3A1 showed increasing methylation frequencies from adenomas to carcinomas, while HOXA9, MAL, and MGMT displayed overall equal methylation frequencies in all tumor subgroups." (PMID 19117505, 2008).